KCNQ1 (potassium voltage-gated channel subfamily Q member 1)
Diseases named in the same sentence as KCNQ1 in open-access papers (continued):
Sharing a sentence is not in itself a finding about the gene and the disease.
type 2 diabetes (continued). "The aims of this study were to measure variation in DNA methylation at the type 2 diabetes locus KCNQ1 and assess its relationship with metabolic measures and with genotype." (PMID 30641161, 2019). "Other consistent loci involve CNTNAP2 (contactin associated protein-like 2) and have been reported associated with several mental diseases, as well as KCNQ1 (voltage-gated KQT-like subfamily Q, member 1) that has been associated with type 2 diabetes." (PMID 31277270, 2019). "DNA methylation in a differentially methylated region ∼769 kb distal to KCNQ1 has previously been associated with the genotype of one these SNPs, rs2334499, suggesting that methylation at the 11p15 locus could be important in the aetiology of type 2 diabetes or its associated traits." (PMID 30641161, 2019). "In this study we explore locus-specific DNA methylation patterns in the gene KCNQ1, which has established links to type 2 diabetes aetiology." (PMID 30641161, 2019). "KCNQ1 rs2237892 and CDKAL1 rs10946398 were identified as a susceptibility gene for type 2 diabetes in GWAS, and each of these genes is associated with β-cell dysfunction." (PMID 31623129, 2019). "Another important physiological function of Kv7.1 was discovered by genome-wide association studies, in which single nucleotide polymorphisms in the KCNQ1 locus were associated with type 2 diabetes in several populations." (PMID 30302399, 2018). "In the present study, an association between KCNQ1 rs2237892 and repaglinide efficacy was observed with respect to HOMA-IR in newly identified Chinese type 2 diabetes patients." (PMID 27857189, 2016). "We confirmed associations of SNPs in KCNQ1, CDKN2A/CDKN2B, CENTD2 and SLC30A8 with type 2 diabetes in Han Chinese." (PMID 25587982, 2015). "Regarding genetic factors, the KCNQ1 and KCNJ15 variants have been reported to affect the development of type 2 diabetes by impairing beta cell function." (PMID 25166121, 2014). "Japanese genome-wide association studies (GWAS) have identified the loci KCNQ1, UBE2E2, C2CD4A-C2CD4B, and ANK1 to be associated with type 2 diabetes." (PMID 23029454, 2012). "It is interesting that type 2 diabetes genes (e.g., KCNQ1 and SLC30A8) showed limited impacts on fasting glucose in the normoglycemic populations, although they also impaired insulin secretion." (PMID 20668700, 2010). "Two additional SNPs, KCNQ1 rs2237892 and TCF2 rs4430796, which were previously genotyped and showed significant association to type 2 diabetes in our samples, were also included into the combined analysis." (PMID 19862325, 2009). "In a study using genotype as a causal anchor to assess future risk of type 2 diabetes, DNAm did not appear to be on the causal pathway between known type 2 diabetes genetic risk variants and type 2 diabetes, with the exception of KCNQ1." (PMID 37202507, 2023). "We did not detect statistically significant interactions between coffee consumption and five SNPs related to type 2 diabetes (CDKAL1 rs7756992, CDKN2A/B rs10811661, KCNJ11 rs5215, KCNQ1 rs163184, and PEPD rs3786897) in the association between coffee and the risk of type 2 diabetes." (PMID 32722593, 2020). "Our results from the blood glucose analysis validated well-established gene loci associated with type 2 diabetes with common SNPs in CDKAL1, SLC30A8, SND1-PAX4, IDE-KIF11-HHEX, CDKN2A-CDKN2B, KCNQ1 and CDC123,33,37,38 and identified a novel locus associated with FBG in DENND5B." (PMID 32355288, 2020). "We did not observe significant interactions by five single nucleotide polymorphisms (SNPs) related to type 2 diabetes (CDKAL1 rs7756992, CDKN2A/B rs10811661, KCNJ11 rs5215, KCNQ1 rs163184, and PEPD rs3786897) in the association between coffee and the risk of type 2 diabetes." (PMID 32722593, 2020). "This association between methylation levels and insulin sensitivity does not overlap with those variants at the KCNQ1 locus previously linked to type 2 diabetes risk via insulin secretion impairment." (PMID 30641161, 2019).
type 2 diabetes (continued). "This SNP is not in substantial LD with any KCNQ1 SNPs previously associated with type 2 diabetes or any other diabetes related metabolic measures." (PMID 30641161, 2019). "Of importance is that KCNQ1 overexpression may lead to decreased levels of insulin and development of type 2 diabetes." (PMID 29259974, 2017). "The expression of KCNQ1 has been found in the human pancreas and in a cultured, insulin-secreting cell line, but the role of Kv7.1 in the molecular pathogenesis of type 2 diabetes still remains unclear." (PMID 29259974, 2017). "Therefore, we note that we identified differential methylation of single CpG sites within 7/59, two CpG sites in 2/59 (BCL11A, AKT2), and consistent changes in six CpG sites in 1/59 (KCNQ1) type-2 diabetes genes." (PMID 25651499, 2015). "Notable exceptions were the KCNQ1 SNPs, which showed prominent ORs for type 2 diabetes." (PMID 25145545, 2014). "A majority of genes associated with type 2 diabetes from this meta-analysis (ADCY5, CDKAL1, CDKN2A/B, HHEX, IGF2BP2, SLC30A8, TCF7L2 and KCNQ1) are involved in pancreatic beta cell function, while two are implicated in insulin sensitivity (PPARG) and adiposity (FTO)." (PMID 25145545, 2014). "Numerous variants in KCNQ1 have also been implicated in type 2 diabetes in several populations, though none were in linkage disequilibrium with rs79972789." (PMID 23424626, 2013). "Mutations in KCNQ1 are associated with hereditary long and short QT syndromes (OMIM#192500 & 609621), Jervell and Lange-Nielsen syndrome (OMIM#220400), familial atrial fibrillation (OMIM#607554), type 2 diabetes." (PMID 24068962, 2013). "Furthermore, the effect size (OR) of rs5945326-A in the present Japanese sample (OR = 1.39) was larger than that in other Japanese type 2 diabetes loci, except for KCNQ1 and TCF7L2." (PMID 23029454, 2012). "Three Japanese GWAS including ours, have identified the association of the potassium voltage-gated channel KQT-like subfamily member 1 (KCNQ1) locus, ubiquitin-conjugating enzyme E2E 2 (UBE2E2) locus and C2 calcium-dependent domain containing 4A (C2CD4A)-C2CD4B locus with type 2 diabetes." (PMID 22046406, 2011). "However, the contribution of the KCNQ1 to the molecular pathogenesis of type II diabetes (T2D) remains to be elucidated." (PMID 21261977, 2011). "KCNQ1, which is located at chromosome 11p15.5 and near a candidate region at 11p13-p12 and mainly encodes a protein for a voltage-gated potassium channel required for the repolarization phase of the cardiac action potential, has been proved to be associated with type 2 diabetes mellitus (T2DM)." (PMID 20701788, 2010). "Although the affected KCNQ1 locus is located in an imprinted genomic region, and KCNQ1 is considered a risk gene for type 2 diabetes, our data show that the C1189T mutation does not alter the epigenetic regulation of gene expression in the imprinted KCNQ1 locus during pancreatic differentiation." (PMID 39055936, 2024). "However, the contribution of KCNQ1 to the pathogenesis of type 2 diabetes is currently unclear." (PMID 34853793, 2021). "Potassium voltage-gated KQT-like (KCNQ1) channels play a role in the intestinal secretion of GLP-1 and glucose-dependent insulinotropic polypeptide (GIP), and polymorphisms in the gene coding for these channels have been linked to type 2 diabetes through a role in insulin release." (PMID 33594477, 2021). "In addition, Kv7.1 channels in the pancreatic ß-cells contribute to the regulation of insulin secretion, and loss of function mutations in the KCNQ1 gene leads to impaired ß-cell insulin secretion, which is associated with type 2 diabetes." (PMID 32695022, 2020). "Recently, a number of GWAS studies have reported a strong association between KCNQ1 (potassium voltage-gated channel, KQT-like subfamily, member 1) and type 2 diabetes mellitus (T2D)." (PMID 28863213, 2017).
type 2 diabetes (continued). "Although large-scaled European GWAS meta-analyses had not detected it, the KCNQ1 locus was shown to be a common susceptibility locus to type 2 diabetes in several ethnic groups including European populations, indicating the importance of performing GWAS in various ethnic groups." (PMID 27115357, 2016). "Genetic variants at KCNQ1 rs151290, KLF14 rs972283, GCKR rs780094 and MTNR1B rs10830963 have been associated with type 2 diabetes mellitus (T2DM), but the results are contradictory in Chinese populations." (PMID 26927145, 2016). "KCNQ1 SNPs have been shown as a more significant contributor to type 2 diabetes than other loci in other Asian populations and because both SNPs (in weak LD) with larger ORs are located on the same gene, it appears that KCNQ1 may truly have a stronger signal in South Asians than in white Europeans." (PMID 25145545, 2014). "In the future, all variants of TCF7L2, KCNQ1, and CDKAL1 could be genotyped to classify clusters of newly diagnosed type 2 diabetes (T2D) in large, multi-centre studies with long-term follow-up." (PMID 41422334, 2025). "Han X., Luo Y., Ren Q., Zhang X., Wang F., Sun X., Zhou X., Ji L.Implication of genetic variants near SLC30A8, HHEX, CDKAL1,CDKN2A/B, IGF2BP2, FTO, TCF2, KCNQ1, and WFS1 in type 2diabetes in a Chinese population." (PMID 35434484, 2022). "Neither Kcnq1 null mice nor patients with deleterious variants show impaired hyperglycemia or glucose intolerance; therefore, it is thought that an increase in expression in pancreatic beta-cells may be linked to the development of type 2 diabetes." (PMID 33336302, 2021). "A DMR was identified in one of the type-2 diabetes genes (PROX1) and differential methylation of the six CpG sites in KCNQ1 were validated by pyrosequencing (see later)." (PMID 25651499, 2015). "In that study, 17 of 40 type 2 diabetes candidate genes were differently methylated, e.g. potassium voltage-gated channel KQT-like subfamily member 1 (KCNQ1) and transcription factor 7-like 2 (TCF7L2)." (PMID 25658116, 2015). "We confirmed the associations of genetic variations in SLC30A8, CDKN2A/CDKN2B, KCNQ1, CENTD2 with type 2 diabetes." (PMID 25587982, 2015). "Sanger sequencing across the KCNQ1 region in the IS1 and IS2 parental lines revealed that IS1 is homozygous for the KCNQ1 non-risk alleles and IS2 is heterozygous for the KCNQ1 type 2 diabetes risk alleles." (PMID 41291239, 2026). "The evidence to date suggests that this is mediated via altered insulin secretion although this was not confirmed in the most recent type 2 diabetes GWAS where the postulated mechanism of action for KCNQ1 was designated unclassified." (PMID 30641161, 2019). "We have previously examined common genetic variation in several candidate gene loci (i.e., KCNQ1, KCNJ11, CDKAL1, and FTO genes) and confirmed some but not all of their associations with type 2 diabetes in the SDS." (PMID 21062480, 2010). "Moreover, 18 obesity and 21 type 2 diabetes candidate genes had CpG sites with differences in adipose tissue DNA methylation in response to exercise (q<0.05), including TCF7L2 (6 CpG sites) and KCNQ1 (10 CpG sites)." (PMID 23825961, 2013). "Recently, several genome-wide and candidate gene association studies have identified many novel genetic loci for type 2 diabetes (T2D); among these genes, CDKAL1, IGF2BP2, SLC30A8, CDKN2A/B, HHEX, FTO, TCF2, KCNQ1, and WFS1 are the most important." (PMID 20509872, 2010). "The effect size for rs12571751 in this study (OR = 1.12) was comparable with those for the previously reported type 2 diabetes loci in Japanese populations, but not as large as that of TCF7L2 (OR = 1.51) or KCNQ1 (OR = 1.42)." (PMID 25951451, 2015).
Arrhythmia (82 papers, 2008 to 2026). Any cardiac rhythm other than the normal sinus rhythm. "Arrhythmia predisposition variants were found in KCNQ1 (n = 11, 0.28%), KCNH2 (n = 2, 0.05%), and SCN5A (n = 5, 0.13%) genes." (PMID 40332002, 2025). "Overall, these findings demonstrate that MAVE scores effectively stratify KCNQ1 variants, predict arrhythmia risk, and outperform current computational tools in clinical contexts." (PMID 41445606, 2025). "Our comprehensive, protein-wide functional approach offers valuable new insights into the KCNQ1 functional landscape and highlights the strong relationship between assay-based functional abnormalities and clinical arrhythmia risk." (PMID 41445606, 2025). "Accurate clinical classification of KCNQ1 variants is critical for advancing cardiovascular genomic medicine and guiding the diagnosis and treatment of inherited arrhythmias." (PMID 41445606, 2025). "Acute IKr blockade has been reported to produce AV-block phenotypes comparable to those observed here, and KCNQ1-dependent IKs contributes to ventricular repolarization and arrhythmia susceptibility." (PMID 41515939, 2025). "In patients with LQTS, swimming has been identified as a relative gene-specific arrhythmia trigger for LQTS1 type (LQTS1) caused by KCNQ1 mutations, the exact mechanism of which is unclear." (PMID 38167168, 2024). "This initial diagnosis was especially supported by a confirmed mutation in KCNQ1 found on a comprehensive arrhythmia panel." (PMID 38808169, 2024). "KCNQ1 contributes significantly to repolarization process, which has been closely linked to cardiometabolic outcomes including cardiac arrhythmias and type 2 diabetes." (PMID 38424222, 2024). "A heterozygous pathogenic variant in KCNQ1, NM_000218.2:c.573_577del, was detected in a case with suspected arrhythmia with a phenotype implicating the KCNQ1 gene." (PMID 36346469, 2023). "Machine learning methods that can predict the outcome of a mutation on KCNQ1 structure and function would be of great value in helping to assess the risk of a heart rhythm disorder." (PMID 35442947, 2022). "Pathogenic variants in KCNQ1 can lead to channel loss-of-function and predisposition to fatal life-threatening irregularities of heart rhythm (arrhythmia)." (PMID 35442947, 2022). "Loss of soluble Klotho promotes cardiac arrhythmia owing to decreased activity of the KCNQ1/KCNE1 channels in cardiomyocytes." (PMID 35406743, 2022). "This KCNQ1-inhibiting effect of gefitinib is implicated in the induction of heart QT prolongation in a guinea pig model, thereby raising a concern of arrythmia when gefitinib is used for NSCLC treatment." (PMID 35216393, 2022). "Accordingly, arrhythmia caused by the R231C KCNQ1 appears to be due to supertrafficking of the channel as compounded by voltage-independent channel activity." (PMID 33600800, 2021). "We validated and optimized the NGS platform with a subset of 46 patients by comparison with Sanger sequencing of coding exons of major arrhythmia risk-genes (KCNQ1, KCNH2, SCN5A, KCNE1, KCNE2, RYR2)." (PMID 31337358, 2019). "The same study used a mouse model carrying a human KCNQ1 knock-in mutation which resulted not only in cardiac arrhythmias but also in seizures and sudden unexpected death in epilepsy (SUDEP)." (PMID 31293497, 2019). "TargetScan indicated that some arrhythmia-related mRNA encoding K channels, such as KCNQ1 and KCNH2, as possible targets of miR-133." (PMID 29843720, 2018). "We evaluated the effect of the KCNQ1 S140G mutation on ventricular arrhythmogenesis and mechanical behavior during normal sinus rhythm and re-entrant arrhythmia using an image-based finite element electromechanical model." (PMID 30108508, 2018). "Our data suggest that use of NPSs, particularly synthetic cathinones, is associated with elevated risk of serious cardiac arrhythmia and sudden death for subjects carrying KCNQ1 G643S." (PMID 29855564, 2018).
Arrhythmia (continued). "Atrial fibrillation is a common cardiac arrhythmia that has been the focus of recent studies aiming to reveal the correlation between atrial fibrillation and KCNQ1 S140G mutations." (PMID 30108508, 2018). "The present data suggest that use of NPSs, synthetic cathinones in particular, confers an elevated risk of serious cardiac arrhythmia and sudden death for KCNQ1 G643S carriers." (PMID 29855564, 2018). "This study further substantiates a causal link between the V307L KCNQ1 mutation and pro-arrhythmia in human ventricles, and establishes partial inhibition of IKs as a potential anti-arrhythmic strategy in SQT2." (PMID 28814790, 2017). "Our results hold implications for designing mechanism-based pharmacologic agents for treating arrhythmia associated with mutations in KCNQ1, such as long QT syndrome type 1 and atrial fibrillation." (PMID 28383569, 2017). "Cardiac arrhythmia in KCNQ1 mutation carriers are triggered by adrenergic drives, e.g., emotional stress, physical exertion, diving, swimming." (PMID 24400285, 2013). "Variation in the 3′-UTR in the KCNQ1 gene also affects the arrhythmia susceptibility significantly, presumably by impacting on the expression of the gene." (PMID 24400285, 2013). "This integration could pave the way for more personalized diagnosis and intervention for patients with KCNQ1 variants and arrhythmia risk." (PMID 41445606, 2025). "KCNQ1 plays a critical role in cardiac electrophysiology and inherited arrhythmia risk." (PMID 41445606, 2025). "He underwent genetic testing, including a comprehensive arrhythmia and cardiomyopathy panel, in April 2013 through GeneDx (Gaithersburg, MD, USA), which confirmed a disease-causing class I variant in KCNQ1 (p.Ala341Gly), a gene with a known association with LQTS type 1." (PMID 38808169, 2024). "This leads to a shorter cardiac cycle and destabilized electrical activity in the heart, raising the chance of arrhythmias); ion channel dysfunction (mutations in the KCNQ1 gene affect the potassium channel responsible for the I_Ks current, which is crucial for cardiac repolarization." (PMID 39767859, 2024). "In addition to KCNQ1R397W, several KCNQ1 mutations affecting the C-terminal A/B helices of KCNQ1 have been associated with LQT1 syndrome (cardiac arrhythmias), which predisposes affected individuals to arrhythmias and sudden death." (PMID 39055936, 2024). "Furthermore, KCNQ1−/− CMs showed arrhythmias even at baseline, suggesting that the complete loss of IKs has a severe effect on myocardial action potentials." (PMID 35765105, 2022). "Prior studies report protective variants against arrhythmia in the coding regions of the KCNQ1 and SCN5A genes and protective variants against Brugada syndrome in a coding region of the SCN10A gene and in a non-coding site downstream the HEY2 gene in the Japanese population." (PMID 33948580, 2021). "In addition to these studies, single case reports on BWS families with KCNQ1 germline variants and multiple miscarriages or episodes of cardiac arrhythmia have been published." (PMID 32393365, 2020). "We next determined which amino acids in HERG and KCNQ1 are targets in arrhythmia-causing mutations." (PMID 18590565, 2008). "The observed correlation between KCNQ1 MAVE function scores and clinical phenotypes highlights the potential of MAVE as a tool for refining variant interpretation and assessing arrhythmia risk." (PMID 41445606, 2025). "Voltage-gated potassium channel (KCNQ1) Channels: KCNQ1 channels contribute to the slow delayed rectifier potassium current (IKs), which is essential for cardiac repolarization and arrhythmia prevention." (PMID 40871490, 2025). "We next examined associations between KCNQ1 MAVE scores and electrocardiographic and arrhythmia phenotypes in 711,448 participants across three large biobanks: All of Us, BioVU, and UK Biobank." (PMID 41445606, 2025).